ENSG00000252139
Gene: Small Cajal body-specific RNA gene on chromosome 18 (49,814,361 to 49,814,443, forward strand). Ensembl gene ENSG00000252139.
Gene Ontology:
Biological process: RNA processing
Cellular component: Cajal body; nucleolus